PECAM1 (platelet and endothelial cell adhesion molecule 1)
Diseases named in the same sentence as PECAM1 in open-access papers (continued):
Sharing a sentence is not in itself a finding about the gene and the disease.
basal cell carcinoma (2 papers, 2013 to 2024). A carcinoma involving the basal cells. "We identified a vascular PECAM1+/Sca1+ cell subpopulation, which was highly enriched in the granulation tissue of skin wounds and in neoangiogenic areas of human basal cell carcinoma." (PMID 23308177, 2013). "Moreover, CD38 signaling modulates PECAM1+/Sca1+/CD38+ cell activation in the healing process implying CD38 as a target for anti-angiogenic therapies in human basal cell carcinoma." (PMID 23308177, 2013).
bladder tumor (2 papers, 2020 to 2023). "Single-cell analysis of bladder tumor samples from BC patients identified the presence of ECs that were positive for platelet endothelial cell adhesion molecule 1 (PECAM1), CD34, and VEGF receptor 1 (FLT1), and further clustering revealed five different subsets of ECs." (PMID 37569686, 2023).
bronchopulmonary dysplasia (2 papers, 2014 to 2016). Bronchopulmonary dysplasia is a chronic respiratory disease that results from complications related to lung injury during the treatment of infant acute respiratory distress syndrome in low-birth-weight premature infants or from abnormal lung development in older infants. "A hyperoxia-induced bronchopulmonary dysplasia study resulted in lower levels of PECAM-1 mRNA and protein." (PMID 27999452, 2016). "Other studies have shown down-regulation of PECAM1 in neutrophils from patients with major trauma and in the lungs of children who died from bronchopulmonary dysplasia after being mechanically ventilated." (PMID 24588994, 2014). "MicroRNA screening indicated miRNAs may participate in the occurrence and development of bronchopulmonary dysplasia, including PECAM-1 expression." (PMID 27999452, 2016).
cardiomyopathies (2 papers, 2023 to 2024). "The expression of PECAM-1 in the myocardium of patients with cardiomyopathies was studied by Western immunoblotting." (PMID 38381272, 2024). "They observed an increase promoter methylation of three genes associated with cardiac angiogenesis in cardiomyopathy, PECAM1, ARHGAP24, and AMOTL2, suggesting that DNA methylation induces altered gene expression in cardiomyopathy." (PMID 37008904, 2023).
cerebral cavernous malformation (2 papers, 2020). A disorder characterized by malformations in the structure of the capillaries in the brain. "ECs that have undergone partial EndMT were identified in the mouse heart (CD31/PECAM-1 and FSP-1) during the progression of cardiac fibrosis as well as in the mouse brain (CD31/PECAM-1 and N-cadherin) in cerebral cavernous malformation (CCM)." (PMID 32373613, 2020).
cerebral malaria (2 papers, 2016 to 2020). A sequestration of Plasmodium falciparum in the brain, which can cause coma and/or seizures. "DC5 PfEMP1s bind platelet-endothelial cell adhesion molecule 1 (PECAM1) and IE adhesion to PECAM1 has been implicated in cerebral malaria." (PMID 27149991, 2016).
chronic thromboembolic pulmonary hypertension (2 papers, 2020). Chronic thromboembolic pulmonary hypertension (CTEPH) is characterized by the persistence of thromboemboli in the form of organized tissue obstructing the pulmonary arteries. "PECAM-1 is also downregulated in plasma of patients with non-resolving DVT and within unresolved thrombi of chronic thromboembolic pulmonary hypertension (CTEPH) patients." (PMID 32168908, 2020).
Co-infection (2 papers, 2020 to 2025). "Co-infection was accompanied by substantial upregulation of inhibitory pathways, including prostaglandin E2 biosynthesis (PGE2-PTGES3-PTGER2/4), cyclophilin A signaling (PPIA-BSG), and PECAM1-mediated interactions, all known to suppress T-cell activation." (PMID 41394852, 2025).
colorectal adenocarcinoma (2 papers, 2019 to 2024). The most common type of colorectal carcinoma. "The Cancer Genome Atlas (TCGA) database mining of 592 colorectal adenocarcinoma patient cohort (COAD, Pan-Cancer Atlas/cBioPortal) consistently linked high expression of EC PECAM-1 and PMN/TAN S100A8 with poor prognosis and disease outcomes." (PMID 38329810, 2024).
Crohn disease (2 papers, 2008 to 2021). A gastrointestinal disorder characterized by chronic inflammation involving all layers of the intestinal wall, noncaseating granulomas affecting the intestinal wall and regional lymph nodes, and transmural fibrosis. "For example, in Crohn’s disease, therapeutic silencing of TNF-α signaling reduced the immunohistochemical expression of the vascular marker cluster of differentiation 31 (CD31; PECAM-1)." (PMID 34206809, 2021).
Fabry disease (2 papers, 2023 to 2024). Fabry disease (FD) is a progressive, inherited, multisystemic lysosomal storage disease characterized by specific neurological, cutaneous, renal, cardiovascular, cochleo-vestibular and cerebrovascular manifestations. "In the context of Fabry disease, elevated levels of adhesion molecules such as VLA4, CR3, ICAM1, VCAM1, and PECAM1 in the bloodstream are closely linked to disease severity." (PMID 39596318, 2024). "This complex network underscores the significant involvement of PECAM1 in immune cell trafficking and inflammation in Fabry disease." (PMID 39596318, 2024). "In Fabry disease, elevated levels of ICAM1, VCAM1, and PECAM1 have been observed in peripheral blood cells." (PMID 39596318, 2024).
Infertility (2 papers, 2021 to 2023). "Some studies have found associations between PECAM-1 and infertility factors such as ovulation disorders, uterine abnormalities, and tubal obstruction." (PMID 38274228, 2023). "PECAM-1 (Platelet Endothelial Cell Adhesion Molecule-1) is a protein implicated in infertility." (PMID 38274228, 2023). "Further research on the relationship between PECAM-1 and infertility should aid in understanding the etiology and treatment of infertility." (PMID 38274228, 2023).
nonalcoholic steatohepatitis (2 papers, 2015 to 2023). "Regarding TNFα signaling via NF-κB in endothelial cells, in animal studies, Pecam1 KO mouse developed nonalcoholic steatohepatitis, whereas Tlr4 KO mouse and Il15 KO mouse were protected from NAFLD." (PMID 37491046, 2023). "Similarly, lack of PECAM-1 resulted in amplified inflammation followed by liver injury in a nonalcoholic steatohepatitis mouse model." (PMID 26177067, 2015).
Parkinson disease (2 papers, 2012 to 2020). A progressive degenerative disorder of the central nervous system characterized by loss of dopamine producing neurons in the substantia nigra and the presence of Lewy bodies in the substantia nigra and locus coeruleus. "In mice, IL4 and PECAM1 also cause neuroinflammation by recruiting mast cells and upregulating the release of various mediators, which may be involved in the formation of Parkinson’s disease." (PMID 33328875, 2020).
plasmacytoma (2 papers, 2014 to 2023). Plasmacytoma is a localized mass of neoplastic monoclonal plasma cells that represents approximately 5% of all plasma cell neoplasms. "PECAM1 (CD31) had previously been found to be expressed at higher levels in extramedullary plasmacytomas compared to primary MM cells." (PMID 37568580, 2023).
silicosis (2 papers, 2018 to 2025). Silicosis is a respiratory disease caused by breathing in (inhaling) silica dust. "Lung tissues from the healthy donors and patients with silicosis showed decreases in PECAM 1/CD31 and HECTD1 staining, which supported our in vitro findings." (PMID 29540674, 2018).
acute leukemia (1 paper, 2013). A clonal (malignant) hematopoietic disorder with an acute onset, affecting the bone marrow and the peripheral blood. "PECAM-1 was conspicuously phosphorylated on tyrosine in Ph+ biphenotypic acute leukemia or ALL cells, which was mostly abolished by treatment with the tyrosine kinase inhibitor imatinib or dasatinib." (PMID 23233201, 2013).
acute pancreatitis (1 paper, 2014). An acute inflammatory process that leads to necrosis of the pancreatic parenchyma. "Adhesion molecules like ICAM-1 and PECAM-1 are scarcely expressed in endothelial cells, but increase in acute pancreatitis." (PMID 25265022, 2014).
alcohol addiction (1 paper, 2020). "The data presented here extend the previously reported association of ADCY9, PECAM1, and IL4 with nicotine or alcohol addiction and psychiatric disorders." (PMID 33328875, 2020).
amyloidosis (1 paper, 2020). A disorder characterized by the localized or diffuse accumulation of amyloid protein in various anatomic sites. "Interestingly, OBSCs from an alternative amyloidosis mouse model (5xFAD) showed similar changes, with a significant increase in PECAM-1+ vessel length and area and a substantial increase in filopodia number compared to WT littermate controls, indicative of conserved mechanisms between models." (PMID 32029735, 2020).
Aortic dissection (1 paper, 2019). Aortic dissection refers to a tear in the intimal layer of the aorta causing a separation between the intima and the medial layers of the aorta. "In the present study, we demonstrated PECAM-1 expression by peripheral blood monocytes was reduced by indomethacin administration in mice receiving BAPN/Ang II infusion before the development of aortic dissection." (PMID 31341173, 2019). "We collected peripheral blood 4 hours after the initiation of BAPN subcutaneous injection and Ang II infusion to see whether PECAM-1 expression is reduced prior to the initiation of aortic dissection." (PMID 31341173, 2019).
asthma (1 paper, 2017). "For example the PECAM-1 (platelet endothelial cell adhesion molecule-1) 125 Val/leu polymorphism is more frequent in asthma patients in comparison with controls." (PMID 28100233, 2017).
delirium (1 paper, 2019). A disorder characterized by confusion; inattentiveness; disorientation; illusions; hallucinations; agitation; and in some instances autonomic nervous system overactivity. "Further, we found that PECAM-1 is associated with increased pNF-H serum levels which is considered as a surrogate biomarker for the estimation of clinical severity of delirium." (PMID 31574089, 2019). "Moreover, serum pNF-H levels, a potential biomarker for the estimation of clinical severity of delirium, were associated with PECAM-1." (PMID 31574089, 2019). "PECAM-1 was associated with increased pNF-H levels, which could be considered as a means to evaluate the clinical severity of delirium-related CNS damage, in patients with serum pNF-H detection." (PMID 31574089, 2019). "In reference to pNF-H, P-selectin may be involved in the development of delirium-related CNS damage and PECAM-1 may contribute to the progression of delirium- related CNS damage." (PMID 31574089, 2019). "Therefore, PECAM-1 might play a crucial role in the progression of the anatomical CNS damage, observed subsequently to delirium onset." (PMID 31574089, 2019). "Our findings suggest that P-selectin and PECAM-1 are two cell adhesion molecules of the BBB potentially participating in the development and progression of postoperative delirium-related CNS damage in reference to the axonal damage biomarker, serum pNF-H." (PMID 31574089, 2019).
dilated cardiomyopathy (1 paper, 2016). Cardiomyopathy which is characterized by dilation and contractile dysfunction of the left and right ventricles. "Mice with deleted PECAM-1, Syndecan-1, and Syndecan-4 are healthy and fertile, although PECAM-1 knockouts suffer from dilated cardiomyopathy and systolic dysfunction." (PMID 27027326, 2016).
falciparum malaria (1 paper, 2008). "The results indicate the significance of specific genetic variants of ICAM1, PECAM1 and CD36 in influencing the outcome of falciparum malaria in Indian populations." (PMID 19055786, 2008). "The data highlights the significance of variations in the ICAM1, PECAM1 and CD36 genes in the manifestation of falciparum malaria in India." (PMID 19055786, 2008).
fallopian tube cancer (1 paper, 2023). A primary or metastatic malignant neoplasm that affects the fallopian tube. "Additionally, elevated PECAM-1 expression has been identified in individuals with fallopian tube cancer and tubal tuberculosis." (PMID 38274228, 2023).
female infertility (1 paper, 2025). Diminished or absent ability of a female to achieve conception. "The metabolite 3-hydroxybutyric acid (3-HB) as well as the protein platelet endothelial cell adhesion molecule-1 (PECAM-1) both have new evidence to be implicated in female infertility without being related to other visible infertility disorders." (PMID 41301859, 2025).
ganglioglioma (1 paper, 2023). A well differentiated, slow growing neuroepithelial neoplasm composed of neoplastic, mature ganglion cells and neoplastic glial cells. "Co-expression of CD34, PAX6, SOX2, and MSI1 (after stringent counter selection against vascular cells using PECAM1, VWF, DCN, and COL1A2), was particularly strongly associated with ganglioglioma neoplastic cell stemness." (PMID 36966348, 2023).
heart transplant (1 paper, 2010). "We found that PECAM1, CXCL9 and CD44 proteins were significantly upregulated in the serum/plasma samples of both renal and heart transplant patients with acute rejection compared with patients with stable graft function." (PMID 20885780, 2010).
heroin addiction (1 paper, 2020). "Our study provides evidence for the association of ADCY9, PECAM1, and IL4 with heroin addiction through stringent bioinformatics analysis." (PMID 33328875, 2020).
Hydrocephalus (1 paper, 2012). Hydrocephalus is an active distension of the ventricular system of the brain resulting from inadequate passage of CSF from its point of production within the cerebral ventricles to its point of absorption into the systemic circulation. "As hydrocephalus development in JAM-C−/− mice C57BL/6 mice strongly suggested the expression of JAM-C in the CNS, we performed double-immunofluorescence stainings for JAM-C and PECAM-1 on brain cryosections from wildtype and JAM-C−/− C57BL/6 mice." (PMID 23029139, 2012).
intracranial meningioma (1 paper, 2021). A meningioma that arises within the cranial cavity. "In intracranial meningioma, ALCAM and PECAM1 (platelet and endothelial cell adhesion molecule 1), as well as selectins, stained highly positive compared to normal control tissues." (PMID 34680335, 2021).
Kawasaki disease (1 paper, 2017). A rare inflammatory disease characterized by an acute febrile, systemic, self-limiting, medium-vessel vasculitis primarily affecting children. "The relationship between PECAM-1 gene polymorphisms and their susceptibility to Kawasaki diseases (KD) is still unclear." (PMID 28512385, 2017). "Our results suggested that the frequencies of CC, GG, and CG genotypes of PECAM-1 gene 373 C/G in the Kawasaki disease group were statistically different from those in the normal control group." (PMID 28512385, 2017). "But no study has identified the possible association between PECAM-1 gene polymorphism and the development of Kawasaki diseases with or without CAL." (PMID 28512385, 2017).
Lewis lung carcinoma (1 paper, 2019). "However, when Lewis lung carcinoma (LLC) cells were implanted into the back skin of Vegfr3-Gap43-Venus BAC Tg mice, Venus was markedly upregulated in the PECAM1-positive endothelial cells in the tumor." (PMID 30601868, 2019).
liver failure (1 paper, 2015). A liver disease characterized by the liver losing or has lost all of its function. "It is also interesting to note that ADIPOQ, β-NGF, CXCL1, CXCL9, CXCL12, IL-16, and PECAM-1 are up-expressed only in those CHC and HCC patients who present a liver failure, and, hence, linkable to the necro-inflammatory activity of the liver." (PMID 26226632, 2015).
lupus nephritis (1 paper, 2023). Glomerulonephritis in the context of systemic lupus erythematosus. "Further studies with contemporaneous measurement of PECAM-1 in plasma and urine should be considered in patients with lupus nephritis." (PMID 37516862, 2023).
Noonan syndrome (1 paper, 2024). Noonan Syndrome (NS) is characterized by short stature, typical facial dysmorphism and congenital heart defects. "In order to search for a role of PTPN11 signaling downstream of PECAM1, we collected blood samples from six Noonan syndrome patients (N1-6), all with a gain-of-function mutation in the PTPN11 gene." (PMID 38236412, 2024).
pemphigus (1 paper, 2021). Pemphigus is a group of rare autoimmune diseases that cause blistering of the skin and mucous membranes (mouth, nose, throat, eyes, and genitals).This conditioncan occur at any age, but often strikes people in middle or older age. "KRT14, a marker of keratinocytes, was significantly higher, and PECAM1, a marker of endothelial cells, was significantly lower in pemphigus cases vs. controls." (PMID 34660634, 2021).
peripheral nerve injury (1 paper, 2022). Injury to a peripheral nerve. "Moreover, PECAM-1 may also contribute to spinal mechanisms of pain because peripheral nerve injury induces an increase in PECAM-1 immunoreactivity in related spinal cord." (PMID 35909446, 2022).
spinal cord ischemia (1 paper, 2018). Reduced blood flow to the spinal cord which is supplied by the anterior spinal artery and the paired posterior spinal arteries. "Significant increases in PECAM-1 expression have been observed in a spinal cord ischemia model, focal cerebral ischemia model, and other peripheral ischemia models and may be due to neutrophil migration." (PMID 30258402, 2018).
tongue cancer (1 paper, 2025). A malignant neoplasm affecting the tongue. "At proteomic level, TBM-02 cell line supernatant demonstrated distinct levels of cytokines IL-6 and IL-8, and growth factors EGF, PECAM-1 and VEGF in comparison to AW13516 which is a tongue cancer cell line." (PMID 41410801, 2025).
type 1 diabetic nephropathy (1 paper, 2005). "PECAM-1 is located near protein kinase C alpha, an enzyme implicated in albuminuria during type 1 diabetic nephropathy." (PMID 16371158, 2005). "PECAM-1, whose gene is also up-regulated in type 1 diabetic nephropathy participates in leukocyte transmigratory processes and is regulated by modulators of NFκB." (PMID 16371158, 2005).
ventricular dilation (1 paper, 2024). "Platelet endothelial cell adhesion molecule (PECAM-1), a regulator of mechanosensory functions, is associated with left ventricular dilation and systolic dysfunction in mice when absent." (PMID 39609399, 2024).
viral encephalitis (1 paper, 2025). Encephalitis resulting from viral infection. "Studies have shown that reduced PECAM1 expression exacerbates BBB leakage and immune cell infiltration in both viral encephalitis and seizure models." (PMID 41007696, 2025).